P2RX4 (purinergic receptor P2X 4)
Diseases named in the same sentence as P2RX4 in open-access papers (continued):
Sharing a sentence is not in itself a finding about the gene and the disease.
colitis (1 paper, 2023). Inflammation of the colon. "To define whether gut microbiota profiles are associated with the deterioration of colitis caused by P2rx4 deletion, we performed a 16S rDNA sequencing in cecal contents." (PMID 37085966, 2023). "Further investigation revealed that the worsening colitis caused by P2rx4 gene ablation may be related to an impaired intestinal mucosal barrier and an altered inflammatory cytokine profile." (PMID 37085966, 2023). "We found that loss of P2rx4 resulted in more severe DSS‐induced colitis than in WT mice." (PMID 37085966, 2023). "To further verify whether the deterioration of colitis caused by P2rx4 deletion is due to gut microbiota dysbiosis, we gave WT and P2rx4−/− mice an antibiotic cocktail (ABX) to consume their gut microbiota before inducing colitis with DSS." (PMID 37085966, 2023). "Since MAPK signals are involved in worsening colitis caused by P2rx4 deficiency, we wanted to test the MAPK‐related protein expression using a Western Blotting assay to that could be impacted by P2X4 receptor activation." (PMID 37085966, 2023). "Finally, we conducted an FMT test to confirm whether worsening colitis caused by P2rx4 ablation is mediated by gut microbiota." (PMID 37085966, 2023). "Therefore, to know whether changes in gut permeability are related to the worsening colitis caused by P2rx4 deletion, we determined the intestinal mucosal permeability by EB exclusion assay." (PMID 37085966, 2023). "Gene ablation of P2rx4 aggravated DSS‐induced colitis accompanying gut microbiota dysbiosis in mice." (PMID 37085966, 2023). "We observed that P2rx4 gene ablation exacerbated colitis while activation attenuated it in mice, which involved the alteration of inflammation, gut microbiota dysbiosis, and intestinal mucosal permeability." (PMID 37085966, 2023). "Because inflammatory mediators are a driving factor in acute colitis, we evaluated the effects of P2rx4 deletion on systemic and intestinal inflammatory responses." (PMID 37085966, 2023). "In this study, it was observed that P2rx4−/− mice were more prone to colitis with a shorter colon than DSS‐treated WT mice (a reduction of ∼35% for P2rx4−/− mice and ∼20% for WT mice)." (PMID 37085966, 2023). "Simultaneously, Cohousing and FMT experiments jointly demonstrated that, after homogenizing the microbial communities of P2rx4−/− and WT mice, the more severe colitis caused by P2rx4 gene deletion was no longer observed." (PMID 37085966, 2023). "Finally, we gave P2rx4−/− mice ivermectin at doses of 0, 2 and 5 mg/kg to further ascertain whether the anti‐colitis action of ivermectin relies on the P2X4 receptor." (PMID 37085966, 2023). "Surprisingly, we found that P2rx4 ablation did not impair ivermectin's anti‐colitis effect, indicating that the P2X4 receptor is not involved in this protection." (PMID 37085966, 2023).
endometrial carcinoma (1 paper, 2022). A malignant tumor arising from the epithelium that lines the cavity of the uterine body. "Eight IRGs were incorporated to construct a nomogram for survival prediction in endometrial carcinoma patients, including CCR7, GNA15, GPR132, LTA, MYC, NOD2, P2RX4 and P2RY2." (PMID 36207698, 2022). "Among these genes, CCR7, MYC and NOD2 have been reported in a large number of tumor studies, including endometrial cancer, while P2RX4, GNA15, and GPR132 genes have few molecular biological experiments to verify their role in endometrial cancer progress." (PMID 36207698, 2022).
Infertility (1 paper, 2018). "It therefore remains to be determined whether and, if so, how the ATP/P2RX4 axis of peritubular cells may be related to testicular fibrotic ECM deposits in men suffering from infertility." (PMID 29362497, 2018).
metastatic cancer (1 paper, 2021). A carcinoma which has spread from the original site of growth to another anatomic site. "In summary, our study found a novel association between genetic variants in TPCN2 and P2RX4 and the risk of developing cancer, metastatic cancer, cancer recurrence at a global level, or various types of cancer at the local level in the UK Biobank population." (PMID 34253731, 2021).
pancreatic cancer (1 paper, 2026). "In contrast to its RNA expression profile, P2RX4 protein levels exhibited differential regulation in human colorectal and pancreatic cancer epithelia due to alternative splicing." (PMID 42231750, 2026). "Here, we aimed to assess whether determining P2RX4 expression status in colorectal and pancreatic cancer patients would allow stratification of potentially responsive patients." (PMID 42231750, 2026). "Given the lower degree of heterogeneity observed in pancreatic cancer, this tumor entity may represent a promising candidate for early-phase clinical evaluation of chemotherapy combined with P2RX4 inhibition." (PMID 42231750, 2026).
preeclampsia (1 paper, 2014). Preeclampsia is a hypertensive disorder of pregnancy that is characterized by new-onset hypertension with proteinuria presenting after 20 weeks of gestation, and depending on mild or severe forms may initially present with severe headache, visual disturbances, and hyperreflexia. "CpG methylation within the P2RX4 promoter was reduced in preeclampsia samples relative to controls in our data, suggesting elevated transcription." (PMID 25247495, 2014). "For example, the expression of Purinergic Receptor P2X, Ligand-Gated Ion Channel, 4 (P2RX4) has been shown to be elevated in both pre-term and term placental samples from preeclampsia cases compared to normal controls." (PMID 25247495, 2014).
tumor (35 papers, 2013 to 2026). "P2RX4 belongs to the P2 purinergic receptor family, which is commonly upregulated in a variety of tumours and is associated with poor prognosis." (PMID 38259456, 2023). "TPCN2 and P2RX4—and cancer in terms of the definition of tumour types, susceptibility, and prognosis." (PMID 34253731, 2021). "Upregulation of P2RX4 has been linked to increased tumor cell proliferation, migration, and invasion through several processes such as the promotion of EMT, autophagy and lysosomal exocytosis, as well as in the modulation of oncogene and tumor suppressor gene crosstalk via unelucidated mechanisms." (PMID 41009609, 2025). "Accordingly, P2RX4 inhibition in combination with chemotherapy was effective exclusively in patient-derived tumor organoids expressing the canonical P2RX4 transcript." (PMID 42231750, 2026). "Subcellular localization of P2RX4 isoforms was analyzed in HeLa cells and patient-derived tumor organoids." (PMID 42231750, 2026). "In this review, we highlighted the role of the purinergic receptor P2RX4 in promoting tumor aggressiveness, particularly in breast and prostate cancers." (PMID 41009609, 2025). "Reversal of P2RX4 knockdown significantly decreased p62 levels, and increase autophagy flux and lysosomal fusion, thus enhancing tumor cells’ aggressive capabilities." (PMID 41009609, 2025). "The comparison results showed that the mRNA expression levels of CDK1 and P2RX4 in PTC tissues were significantly higher than those in non-tumor thyroid tissues." (PMID 36333684, 2022). "Previous studies demonstrated that P2RX4 acts as a regulator of tumour development by playing a critical role in inflammation and immune cell function, which are part of the pathophysiological processes that occur in the tumour microenvironment." (PMID 34253731, 2021). "And the positive correlation between ITGA5, NOD2, P2RX4, RIPK2, SLC7A1 and immune score indicated that the tumor tissue in the high-risk group is highly infiltrated by immune cells, which is consistent with risk score." (PMID 33828988, 2021). "Inhibition of P2RX4 did not cause any direct cell death but stunted the growth rate of PCa tumor cells in mouse xenograft model by 39.4% in 2 weeks while in cell culture model, growth rates were reduced by 50–70%." (PMID 41009609, 2025). "Given its role in promoting tumour formation, P2RX4 has emerged as a potential therapeutic target." (PMID 38259456, 2023). "Consistent with our findings, recent studies have confirmed that P2RX4 could enhance tumor growth and has been considered a potential treatment target." (PMID 36769510, 2023). "Moreover, P2RX4 may play a vital role in regulating tumor development through inflammation and immune responses in the microenvironment." (PMID 36333684, 2022). "The analysis results showed that the expression levels of Purinergic genes GNAI2, GNAI3, P2RX4, P2RX7, and PANX1 were significantly higher in tumor tissues than in normal tissues, consistent with the mRNA expression results." (PMID 38180750, 2024). "We obtained the protein expression data of Purinergic genes GNAI2, GNAI3, GNAO1, P2RX4, P2RX7, and PANX1 in normal tissues and tumor tissues in the UALCAN database." (PMID 38180750, 2024). "Overall, the effect of PTPN12, IDH2, P2RX4, and KDELR2 on tumor immune cell infiltration is a complex process that typically involves multiple molecular pathways and signaling pathways." (PMID 37563735, 2023). "Our future goals are to examine the effects of eATPase inhibition and P2RX4 and P2RX7 activation on TNBC models in vivo in the context of an intact tumor microenvironment and functional immune system." (PMID 35515134, 2022). "It was observed that silencing of P2RX4 leads to downregulation of mesenchymal markers Vim and Twist as well as the upregulation of epithelial markers Zo1 and Cdh1, reversing EMT and reducing tumor cell invasion." (PMID 41009609, 2025).
tumor (continued). "Also, we identified novel predicted tumor-suppressive ligands (SLIT3, DCN, CCN3, THBS1, INHA and INHBA), proteins (DNASE1L3, SULF1, PTEN, OAS1, and DAB2IP), and receptors (P2RX4, CDHR2, PTPRJ, and PTPRH) in MSC1 cells." (PMID 40564222, 2025).
cancer (30 papers, 2015 to 2025). A tumor composed of atypical neoplastic, often pleomorphic cells that invade other tissues. "Future studies should delve deeper into the molecular mechanisms underlying P2RX4-mediated cancer progression, such as the role of P2RX4 in PTEN-PHLLP crosstalk, and to engineer novel anti-P2RX4 therapeutics with improved efficacy and selectivity." (PMID 41009609, 2025). "Certain genetic variants of P2RX4 are associated with an increased risk of developing these cancers." (PMID 41009609, 2025). "Here we discovered a novel association between polymorphisms in TPCN2 and P2RX4 in cancer at the global level for subtypes of cancer." (PMID 34253731, 2021). "For the first time, we report novel associations between genetic variants of TPCN2 and P2RX4 and cancer/cancer subtypes in the UK Biobank’s population." (PMID 34253731, 2021). "We identified polymorphisms in the TPC2N and P2RX4 genes that are significantly associated with both an increased and decreased risk for developing cancer or a subtype of cancer in the UK Biobank." (PMID 34253731, 2021). "In this study, we leveraged a large, single resource, the UK Biobank, to explore for the first time the relationship between genetic variants of two endolysosomal proteins, TPCN2 and P2RX4, and human cancer." (PMID 34253731, 2021). "By developing targeted therapies against P2RX4, we may be able to improve patient outcomes and combat the devastating effects of aggressive cancers as shown in the case of targeting P2RX4 in pathogenic plasma cells." (PMID 41009609, 2025). "P2RX4 polymorphism has been linked to the development of various cancers." (PMID 41009609, 2025). "We also showcased some P2RX4 polymorphisms that could be linked to an increased risk of cancer." (PMID 41009609, 2025). "T cells from patients can be harvested and engineered to express a chimeric antigen receptor (CAR) specific to P2RX4 to effectively recognize and eliminate cancer cells overexpressing P2RX4." (PMID 41009609, 2025). "Further investigation is needed to fully elucidate the molecular mechanisms by which P2RX4 drives cancer progression and to translate these findings into effective and safe clinical therapies." (PMID 41009609, 2025). "Other than a promising target for inflammatory diseases, P2RX4 has potential to be a good cancer target but was mostly overlooked until recently." (PMID 41009609, 2025). "Targeting P2RX4 presents a promising therapeutic approach for combating some of these aggressive cancers." (PMID 41009609, 2025). "Silencing P2RX4 interferes with this crosstalk and TGFβ-1-induced EMT was prevented and key PCa markers linked with cancer aggressiveness such as MMP9 were downregulated." (PMID 41009609, 2025). "CAR-T cell therapy can offer another powerful approach to target P2RX4-expressing cancers." (PMID 41009609, 2025). "P2RX4 is an ion channel activated by extracellular ATP, and could also function as a pro-inflammatory receptor in cancer progression." (PMID 38157255, 2023). "Emerging evidence has uncovered the role of P2RX4 in cancer biology, including cancer pain." (PMID 36333684, 2022). "Similarly, engineering of bispecific antibodies that concurrently bind P2RX4 and CD3 could recruit and signal T cells to attack cancer cells that overexpress P2RX4." (PMID 41009609, 2025). "P2RX4 might demonstrate distinctive roles in different types of cancer." (PMID 34253731, 2021). "In addition, conjugation of anti-P2RX4 Ab with cytotoxic drugs (ADCs) or oligonucleotides (AOCs) can deliver anti-cancer drug payloads, which could selectively and potently target and kill cancer cells that overexpress P2RX4." (PMID 41009609, 2025). "Increased P2RX4 expression was observed to also promote lysosomal exocytosis, allowing higher concentrations of CTSD to be released into the extracellular matrix, promoting degradation of the ECM and enhancing the invasive properties of cancer cells." (PMID 41009609, 2025).
cancer (continued). "Currently, there is no P2RX4-targeting drug on the market for cancer therapy." (PMID 41009609, 2025).
inflammation (5 papers, 2015 to 2022). Aberrant reaction of the microcirculation characterized by movement of fluid and leukocytes from the blood into extravascular tissues. "Since P2RX4 is expressed in alveolar macrophages and shows an increased expression in MNCs isolated from COPD patients, we suggested monocyte-derived cells to play a pivotal role in P2X4-mediated effects in acute cigarette smoke-induced airway inflammation." (PMID 35676684, 2022).
P2RX4 also shares sentences with these, for which no sentence is quoted: ischemic stroke (13 papers); amyotrophic lateral sclerosis (10); Anxiety (9); Sepsis (9); astrocytoma (7); Alzheimer disease (6); atherosclerosis (6); brain injury (6); infection (6); alcohol-use disorders (5); Cognitive impairment (5); diabetes (5); experimental autoimmune encephalomyelitis (5); neurodegenerative disease (5); peripheral nerve injury (5); psychiatric disorder (5); Arthritis (4); glioma (4); intracerebral hemorrhage (4); ischemia (4); Parkinson disease (4); status epilepticus (4); autoimmune encephalitis (3); colorectal cancer (3); migraine (3); type 2 diabetes (3); allergic reactions (2); brain tumor (2); cardiovascular disease (2); cerebral infarction (2).
A further 98 diseases each share a sentence with P2RX4 in 2 papers or fewer.